IGSF1 (immunoglobulin superfamily member 1)
Diseases named in the same sentence as IGSF1 in open-access papers (continued):
Sharing a sentence is not in itself a finding about the gene and the disease.
congenital hypopituitarism (1 paper, 2022). "In recent years, variants in immunoglobulin superfamily member 1 (IGSF1) have been associated with congenital hypopituitarism." (PMID 35456429, 2022).
Developmental delay (1 paper, 2025). "Developmental delay in patients with CCH can be attributed to syndromes involved in cerebral abnormalities like midline brain defects, or to mutations in genes like IGSF1 or CHD7 that are associated with neurologic involvement." (PMID 39008607, 2025).
glioma (1 paper, 2020). A benign or malignant brain and spinal cord tumor that arises from glial cells (astrocytes, oligodendrocytes, ependymal cells). "This is an important observation since the combined blocking of the IgSF1-VISTA pathways, along with other immune checkpoints could be of interest in glioma treatment." (PMID 33604291, 2020).
hepatocellular carcinoma (1 paper, 2020). A malignant tumor that arises from hepatocytes. "In a patient with hepatocellular carcinoma who achieved CR status, the CCF value decreased, whereas DPYD and IGSF1 increased significantly." (PMID 32738923, 2020).
hygroma (1 paper, 2016). "Although one patient was treated for frontoparietal hygroma, we do not believe that these results warrant standard cerebral imaging in patients with IGSF1 deficiency and a normal head circumference, given the low prevalence and benign character of BEH." (PMID 26840047, 2016).
hypophosphatemic rickets (1 paper, 2024). Rickets due to low serum phosphate concentrations, the cause of which can be nutritional or genetic. "For example, patients with pathogenic variants in NFKB2 or IGSF1 or the dual diagnosis of patient 37 (neurofibromatosis and hypophosphatemic rickets) would have been missed by targeted panel sequencing." (PMID 37940764, 2024).
prolactinoma (1 paper, 2022). "Two additional genes, IGSF1 and IRS4, were massively and specifically overexpressed in the F6 prolactinoma." (PMID 35978432, 2022).
prostate carcinoma (1 paper, 2022). A carcinoma that arises from epithelial cells of the prostate gland. "On the other hand, the expressions of IGSF1 and CRISP3 are known to be androgen receptor (AR)-dependent and characteristic in prostate cancer cells." (PMID 35976950, 2022).
tumor (6 papers, 2012 to 2025). "The expression of IGSF1 is associated with the invasion and metastasis of neoplasms by mediating homotypic and heterotypic intercellular adhesion and binding." (PMID 28678795, 2017). "Moreover, several candidate genes, such as VWA5A, ABCG2, A2M and IGSF1, associated with tumor suppression, growth and age were expanded, implicating their potential roles in the exceptional longevity of turtles." (PMID 37508370, 2023). "CX3CL1, AGT, ATP1A2, and IGSF1 mRNAs proved to be significantly down-modulated in the BM-infiltrating GD2 positive fractions compared to primary tumor cells (P<0.0001, P = 0.0325, P = 0.0196, P = 0.0047, respectively)." (PMID 22253825, 2012). "Likewise, the following marker genes were selected for analysis in PF tumours: LAMA2, ALDH1L1, SLC6A13, IGSF1, and CXorf67 for PFA; and NELL2, DNAH1, CEP83, C9orf72, and NXNL2 for PFB tumours." (PMID 34314101, 2021). "Moreover, mRNA expressions of CA14, RPE65, IGSF1, SLC18 A2 and CPNE6 were significantly lower in PCa samples compared to benign samples, while HJURP, COMP, KRTAP5-1, VGF, SSTR1, LINC01612, NAALADL2-AS2, AMH and ARHGDIG were elevated in tumor samples (p < 0.05)." (PMID 40592939, 2025).
endocrine disorders (2 papers, 2022 to 2025). "However, the detailed phenotypic data we provide about the family add significant information to the existing literature on IGSF1-related endocrine disorders." (PMID 41462822, 2025).
IGSF1 also shares sentences with these, for which no sentence is quoted: Infertility (2 papers); primary congenital hypothyroidism (2); thyroid cancer (2); acromegaly (1); anorexia nervosa (1); congenital adrenal hyperplasia (1); congenital nystagmus (1); depression (1); fragile X syndrome (1); hepatoblastoma (1); lymphoma (1); Macrocephaly (1); metabolic syndrome (1); myonecrosis (1); neurofibromatosis (1); Nystagmus (1); ovarian carcinoma (1); Secondary hypothyroidism (1).